TFEB (transcription factor EB)
Diseases named in the same sentence as TFEB in open-access papers (continued):
Sharing a sentence is not in itself a finding about the gene and the disease.
tumor (continued). "The primary tumour occurred in the native kidney and only focally showed biphasic morphology whereas the metastasis, among others to the transplant kidney, showed nonspecific, albeit different morphology, but both had consistent TFEB translocation." (PMID 37415400, 2024). "We found only a single small focus with biphasic morphology typical for TFEB-altered tumours." (PMID 37415400, 2024). "FISH with TFEB 5′ and 3′ probes showed a split-apart signal in tumor cells." (PMID 38386415, 2024). "Small molecule inhibitors targeting TFEB have also been developed and tried for tumor therapy." (PMID 38926803, 2024). "Moreover, the knockdown of TFEB in tumor cells via shRNA not only decreased the mRNA levels of the lysosome biogenesis genes but also levels of these antigen presentation genes induced by 4-OI and thimerosal treatment." (PMID 39349845, 2024). "Likewise, activation of eIF2α and TFEB endows cancer cells with the capacity to increase antioxidant transcription factors and generate antioxidant substances, which assists tumor cells to maintain oxidant-antioxidant homeostasis." (PMID 37021084, 2023). "Further single-nucleus-RNA-sequencing revealed that TAM from LP diet-treated MYC-PyMT tumor had higher transcripts for phagolysosome biogenesis, phagocytosis, and endocytosis due to the nuclear translocation and transcriptional regulation of TFEB/TFE3." (PMID 37884533, 2023). "In addition to that, tumor cell‐derived TGFβ can promote M2 polarization by suppressing transcription factor EB (TFEB) activation and expression in macrophages." (PMID 36794651, 2023). "Ten tumors had not only heterogeneous morphologies but also a broad immunohistochemical profile: the tumor cells consistently moderately to strongly expressed Melan-A, Vimentin and TFEB; however, they showed only weak–moderate positivity for HMB45, AE1/AE3, P504s and CD10." (PMID 36830782, 2023). "The CC enrichment analysis results of this research were consistent with previous reports, where TFEB-mediated endocytosis and phagocytosis could promote tumor growth." (PMID 36765702, 2023). "Thus, the overexpression of the dephosphorylated form of TFEB delays tumor growth driven by Rac1, showing a positive activation of the Rac1-TFEB axis in tumorigenesis." (PMID 35159248, 2022). "Several recent studies have also focused on the function of TFEB in tumor cell metabolism." (PMID 35045880, 2022). "Aberrant activation of TFEB is closely related to tumor oncogenesis and development." (PMID 35970822, 2022). "In AML cells, TFEB functions as a tumor suppressor by inducing differentiation and death." (PMID 35526025, 2022). "Given that TFEB is the master transcription factor in the regulation of lysosomal biogenesis and autophagy, we thus wondered whether CHAF1A could modulate tumor autophagy process via TFEB activation." (PMID 35773729, 2022). "TFEB also regulated HLA-A expression, which increases the tumor immunogenicity of OC." (PMID 34091590, 2021). "For example, the inhibition of TFEB is noted to enhance metabolic pressure or increase chemotherapy sensitivity for tumor cells, while upregulation of TFEB activity is capable of migrating oxidative stress and facilitating the clearance of inflammatory substances in inflammatory states." (PMID 34490237, 2021). "The function of TFEB in tumor prognosis is seemingly controversial." (PMID 33803301, 2021). "Interestingly, TFEB also regulated HLA-A expression, which increases the tumor immunogenicity of OC." (PMID 34091590, 2021). "TFEB and related proteins frequently behave as oncoproteins, as they have a key role in the progression of different cancer types through the transcriptional control of different processes contributing to tumor-cell survival, metastasis, and chemoresistance." (PMID 34685734, 2021).
tumor (continued). "It has been reported that TFEB may contribute to the development and progression of tumor by upregulating autophagy and endocytosis to meet the metabolic requirement in pancreatic and prostate cancer cells." (PMID 34490237, 2021). "The TFEB knockdown led to a significant inhibition of the tumor growth." (PMID 33513833, 2021). "It is worth investigating why autophagy caused by mTOR makes the tumor more sensitive, but autophagy induced by TFEB does not show this." (PMID 34830772, 2021). "In tumor-associated macrophages, TFEB acts as a major switch of both canonical and non-canonical pathways, leading to attenuation of the tumor-supporting phenotype." (PMID 33912071, 2021). "More evidence supports a role for TFEB in the tumor microenvironment." (PMID 33912071, 2021). "This study aimed to investigate whether resistance to cisplatin (CDDP), the standard treatment for OC, is due to the remodeling of the tumor immune microenvironment by the transcription factor EB (TFEB)." (PMID 34091590, 2021). "In this study, we found that TFE3 is also a potent tumour promotor just like TFEB in ccRCC." (PMID 33145941, 2020). "TFEB regulates TAM polarization in the tumor microenvironment." (PMID 32486098, 2020). "In this study, we propose that TFE3 but not TFEB is essential for tumour survival which was associated with the poorer survival of cancer patients." (PMID 33145941, 2020). "Additionally, we also performed IHC staining of the tissue sections and observed significantly low levels of both SIRT2 and TFEB levels in the NSCLC tumor tissues." (PMID 33344455, 2020). "We have found that the expression of TFE3 is higher than TFEB in tumour cells and patients." (PMID 33145941, 2020). "Akt is central to many hallmarks of cancer by promoting cell survival via inhibition of the apoptotic protein Bad, overcoming cell cycle arrest, facilitating glucose metabolism, inhibiting autophagy via regulation of the lysosomal biogenesis controller TFEB, and promoting tumor angiogenesis." (PMID 31500569, 2019). "It is also worth noting that CQ treatment alone is sufficient to induce TFEB nuclear translocation and activation of lysosomal and autophagy genes, which may contribute to tumor regression in combination therapy." (PMID 30979895, 2019). "It is possible that the EAC tumor might suppress the activity of mTOR in heart, which could contribute to the hyperactivation of TFEB and FoxO3a, resulting in increased proteolysis by autophagy and proteasome degradation." (PMID 29618792, 2018). "Moreover, TFEB knockdown also hindered the amelioration of tumor microenvironment by CQ-conditioned macrophages." (PMID 29491374, 2018). "Moreover, TFEB expression is very high in the tumor, compared to TFEB expression levels observed otherwise in normal kidney tissues." (PMID 26654961, 2015). "Moreover, TFEB may play a role in angiogenesis, facilitating the formation of new blood vessels that supply oxygen and nutrients to the tumor and contributing to metastasis." (PMID 39000232, 2024). "Interestingly, hyperactivation of TFEB in FLCN-deficient or glutamine-deprived DCs results in impaired priming of T cells, whereas TAMs require increased TFEB and TFE3 activity to impair tumor growth." (PMID 38411744, 2024). "This prompted us to investigate whether the 4-OI induces tumor immunogenicity depending on TFEB." (PMID 39349845, 2024). "Moreover, TFEB and TFE3 exhibit overlapping functions and are implicated in genetic rearrangements that regulate DNA damage, proliferation and drive the formation of tumor cell 52-54." (PMID 38481802, 2024). "In addition to this, it has also been found that TFEB-amplified RCC exhibits a higher tumor aggressiveness than TFEB-rearranged tumors, and the 5-year survival rate for TFEB-amplified RCC is only 48%, while TFEB-translocated RCC progresses more slowly than TFE3-rearranged RCC." (PMID 37367052, 2023). "Furthermore, TFEB-depleted PDAC cells have limited capacity for orthotopic tumor growth." (PMID 36746928, 2023).
tumor (continued). "Thus, to tolerate incoming drugs, the tumor cells have to activate lysosomal biogenesis, which might be driven by TFEB, a master regulator of lysosomal gene network." (PMID 35053335, 2022). "Finally, Pt might regulate TFEB activity at the level of its interaction with the chromatin of tumor cells." (PMID 35053335, 2022). "Therefore, this study aimed to investigate whether TFEB is involved in cisplatin (CDDP) resistance by regulating the tumor immune microenvironment in OC." (PMID 34091590, 2021). "We hypothesized that TFEB is not essential for tumor survival but is associated with CDDP resistance." (PMID 34091590, 2021). "This study explored whether TFEB is involved in remodeling the tumor immune microenvironment in OC." (PMID 34091590, 2021). "Furthermore, removing ZKSCAN3 synergizes with TFEB expression in tumor inhibition." (PMID 30979895, 2019). "Thus, a lower rate of autophagy–lysosomal activity within a tumor, as indicated by TFEB inhibition, either at an early stage or during progression, or both, might cause more aggressive disease." (PMID 30979895, 2019). "In order to evaluate whether there was an expression effect of TFEB being overexpressed, we examined whether genes that previously had been reported as upregulated in transiently TFEB-overexpressed HeLa cells were also affected in the tumor (TFEB curve)." (PMID 26654961, 2015). "TFEB‐amplified RCCs however exhibit more aggressive behaviour and the distinction from ESC RCC, largely an indolent tumour, is important." (PMID 41384711, 2026). "We also described how autophagy activation, due to TFEB overexpression, plays a critical role in cilia disassembly in CCA, favoring tumor growth." (PMID 40189703, 2025). "Stresses promoting an MITF-to-TFEB-to-TFE3 switch will lead cells to suppress proliferation, reprogram metabolism, and impact tumor immune cell infiltration quantitatively and qualitatively." (PMID 41275493, 2025). "This study aimed to further explore the role of ACSS2 and TFEB in HNSCC and how they affect the biological behavior of tumor cells by regulating autophagy." (PMID 40858538, 2025). "Further factors promoting pro-tumor autophagy and drug resistance include AMPK, ER stress factors (GRP78, JNK), the transcription factor TFEB (transcription factor EB), and sirtuins." (PMID 39935431, 2025). "In a breast cancer model, a low-protein diet activates the mTORC1 pathway in macrophages via TFEB and TFE3-dependent mechanisms, while inhibiting mTORC1 signaling in tumor cells, thereby slowing tumor growth." (PMID 39905317, 2025). "Herein, the knockdown of TFEB in TNBC cells strongly inhibited mammosphere formation and tumor initiation." (PMID 39814550, 2025). "In line with our previous findings, tumor areas showed strong nuclear staining for TFE3, TFEB, and SOX9." (PMID 40189703, 2025). "Knockdown of circRHCG reduced tumor growth, metastasis, and M2 polarization through the BTRC/TFEB axis in vivo." (PMID 38287113, 2024). "In mitophagy pathway, a total of seven proteins belonged to Stage I unique up-regulated proteins, among which TFEB, BNIP3L and SP1 were either statistical significantly up-regulated in Stage I when compared to middle and late stage tumor groups." (PMID 38182978, 2024). "LncRNA XXYLT1-AS2, highly expressed in HCC plasma, promotes tumor growth by inhibiting autophagy and enhancing proliferation, migration, and invasion of HCC cells, through the degradation of TFEB via the ubiquitin proteasome pathway." (PMID 39315094, 2024). "Collectively, these observations suggested that circRHCG contributed to tumor progression and M2 polarization through the BTRC/TFEB axis in vivo." (PMID 38287113, 2024). "For diagnosis, demonstration of TFEB alteration using FISH or sequencing techniques is mandatory, as these tumours exhibit a broad morphologic range." (PMID 37415400, 2024).
tumor (continued). "Subsequently, TRIM25 promotes the nuclear translocation of transcription factor EB (TFEB) and transcription of autophagy related genes by increasing K63-polyubiquitination of TFEB, thereby reducing tumor sensitivity to PTX." (PMID 38926803, 2024). "The platinum-metformin conjugate promotes the degradation of PD-L1 through the AMPK/transcription factor EB (TFEB) pathway and enhances the anti-tumor immune effect in NSCLC." (PMID 39845945, 2024). "Our results revealed that the knockdown of TFEB resulted in decreased expression of MHC-I and the MHC-I/SIINFEKL complex on EG7 tumor cells following stimulation with itaconate and thimerosal." (PMID 39349845, 2024). "This disruption not only aligns with the typical cytoplasmic characteristics but also explains the tumor’s positive immunohistochemical staining for TFE3 and wild-type MITF, as lysosomal inhibition activates the transcription factors MITF, TFE3, and TFEB." (PMID 39372871, 2024). "Although TFEB genes are altered in TFEB-altered RCC, the characteristics of tumor growth vary considerably between different patterns of alteration." (PMID 37367052, 2023). "To further confirm the relevance of modulating EGR1 to reduce TFEB-driven oncogenic properties, we developed 3D cultures from HeLa-FLCN KO cells to mimic the tumor microenvironment better." (PMID 36888606, 2023). "The impact of TFEB knockdown and its family members TFE3 and MITF on PDAC tumor growth has been evaluated in subcutaneous xenografts, but not in orthotopic models, that better recapitulate human disease." (PMID 36746928, 2023). "Rapamycin significantly decreased tumor growth in both WT and TSC2 KO xenografts consistent with decreased TFEB nuclear localization." (PMID 36357396, 2022). "In order to further characterize potential functional redundancy of TFEB and TFE3 in the TSC2 KO background, we performed RNA-seq on tumor xenografts grown from WT, TSC2 KO, and TFEB KO, TFE3 KO and double TFEB/TFE3 KO cells." (PMID 36357396, 2022). "Previous studies have indicated that TFEB-driven autophagy is indespensible for TGF-β-induced pancreatic tumorigenesis, promoting tumor cells migration ability and in vivo metastasis." (PMID 35773729, 2022). "Unexpectedly, mTORC1 inhibition with rapamycin actually promoted TFEB phosphorylation in TSC2 KO cells and xenografts, restored TFEB cytosolic localization and potently inhibited TSC2 KO tumor xenograft growth." (PMID 36357396, 2022). "Given that little was reported about the roles of TFEB in DLBCL, we found that CHAF1A mainly depends on activated TFEB to drive tumor progression." (PMID 35773729, 2022). "A novel modulations of TFEB activity at the translation level has emerged, in which TFEB translation is suppressed by both of MA3 domains within programmed cell death 4, which is a tumor suppressor propitious to lysosome dysfunction related diseases." (PMID 33679452, 2021). "Transcription factor EB (TFEB), a member of the MiT family, is dysregulated in different cancers and exerts specific biological functions within the tumor microenvironment." (PMID 33732651, 2021). "TFEB knockdown in EO771 or LLC-derived C57BL/6 mice resulting in enhanced angiogenesis, tumor growth and reduced infiltration of CD8+ T cells." (PMID 32486098, 2020). "TFEB and TFE3 chromosomal translocations were found in clear cell renal cell carcinoma (RCC), and tumor progression is enabled by an induction of cyclin D2, cyclin D3, and p21." (PMID 31569540, 2019). "TFEB, a transcription factor essential for lysosomal function, is highly activated in PDAC and its knockdown reduces tumor progression and impairs autophagy due to lysosomal dysfunction." (PMID 27626694, 2016). "This tumor is characterized by the translocation of Xp11.2, with the gene fusions involving the TFE3 transcription factor gene or TFEB." (PMID 25274276, 2014).
tumor (continued). "TFEB activation in the CLEAR, RRAGC, UVRAG, CSTB, M6PR, and IGF2R factor expression levels, strengthens lysosome gene expression, improves lysosome function and autophagy, and provides nutrition for tumor cells." (PMID 40858538, 2025). "The metastatic nodules also had no distinctive biphasic morphology, but both metastasis and primary tumour samples showed TFEB translocation without amplification in FISH analysis." (PMID 37415400, 2024). "As exosomes play important roles in shaping tumor microenvironment, we hypothesized that TNBC cell-derived exosomes might regulate macrophage polarization via delivering circRHCG and adjusting TFEB expression, thus regulating TNBC progression." (PMID 38287113, 2024). "The upregulation of BCAA levels did not result in a tumour‐promoting effect, consistent with its tumour growth‐promoting function, and cells after TFEB knockdown inhibited growth and proliferation." (PMID 38938061, 2024). "A previous report shows that overexpression of TFEB in tumor cells could up-regulate the HLA-ABC expression and consequent tumor antigenicity." (PMID 39349845, 2024). "In support of a critical role of TFEB under stress, TFEB depletion reduces anchorage-independent, clonogenic, and tumor (present study) growth despite the absence of a significant effect when cultured under normal 2D conditions." (PMID 36746928, 2023). "In contrast, torin did not significantly affect tumor growth, consistent with the lack of effect on TFEB nuclear localization, despite suppressed phosphorylation of classic mTORC1 substrates (p-4E-BP1 and p-p70S6K) in TSC2 KO tumor lysates." (PMID 36357396, 2022). "In contrast to the apparent redundancy of TFEB and TFE3 for tumor growth in vivo, in vitro results suggested that single TFEB or TFE3 KO may be sufficient to dampen the phosphorylation of direct mTORC1 substrates (p-4E-BP1 and p-p70S6K)." (PMID 36357396, 2022). "The tumor suppressor FLCN and its binding partner FNIP2 comprise the primary GAP complex activating RagC/D and are accordingly crucial for the phosphorylation of TFEB/TFE3 by mTORC146,50." (PMID 36357396, 2022). "Given that previous studies showed that SPOP could restrict tumor autophagy via p62, we thus questioned whether SPOP could depend on CHAF1A/TFEB to regulate autophagy." (PMID 35773729, 2022). "We reasoned that a cohort of TFEB target genes might include ATP7B, whose elevated expression confers Pt-resistance in tumor cells." (PMID 35053335, 2022). "Downregulation of TFEB induces macrophage polarization in the TME and promotes tumor progression." (PMID 33732651, 2021). "We also found that expression of TFE3 but not TFEB was positively correlated with the levels of PD‐L1 in RCC tumour cell lines by CCLE database." (PMID 33145941, 2020). "Moreover, when TFEB and TFE3 were knocked down in the cancer cells, the favorable interaction between MTX and 3,4‐DC leading to stronger tumor growth reduction than with MTX alone was lost." (PMID 31609086, 2019). "These tumours are characterized by the occurrence of recurrent chromosomal translocations, which result in disruption and fusion of either the TFE3 or TFEB genes, both members of the MiT family of basic helix-loop-helix/leucine-zipper transcription factor genes." (PMID 24877033, 2014). "Further experiments found that TMX2 relieved LR and amplified the anti-tumor impact of lenvatinib in HCC by suppressing autophagy and mitophagy, which was achieved through the inhibition of karyopherin subunit beta (KPNB) 1's nuclear export and transcription factor EB (TFEB) 's nuclear import." (PMID 40083703, 2025). "We analyzed the TCGA-LUAD dataset (n = 585): after excluding 8 cases because of the lack of information about tumor stage and 59 cases classified as “normal tissues”, we analyzed the expression of TFEB, ABCC1 and ABCA1 mRNA in the remaining cohort of 531 cases of primary tumors." (PMID 39107857, 2024).